ANO1 (anoctamin 1)
Diseases named in the same sentence as ANO1 in open-access papers (continued):
Sharing a sentence is not in itself a finding about the gene and the disease.
breast cancer (continued). "In other cancers, such as HNSCC and breast cancer, ANO1 is also regulated by other factors, including DNA methylation and acetylation, lncRNAs, and circular RNAs (circRNAs)." (PMID 40396170, 2025). "Dysregulated ANO1 expression promotes oncogenic progression in multiple malignancies, including breast cancer, gastric cancer, and head and neck squamous cell carcinoma (HNSCC)." (PMID 41155636, 2025). "The intracellular Cl- regulation by ANO1/ClC-3 is closely related to the transcription of the HER2 gene in HER2-positive breast cancer cells." (PMID 39744692, 2025). "Upregulation of ANO1 has been shown to stimulate ERK1/2 signaling in breast cancer cells via CaMKII- and EGFR-mediated pathways." (PMID 40356890, 2025). "The resistance to Trastuzumab can be overcome by treatment with ANO1 inhibitor in mice with prostatic and breast cancer." (PMID 40396170, 2025). "Meta-analysis indicates that the overexpression of ANO1 is strongly correlated with poor prognosis and reduced long-term survival in several epithelial-derived malignancies, including breast cancer, HNSCC, ESCC, and CRC." (PMID 40356890, 2025). "Collectively, these findings underscore the critical role of ANO1 in breast cancer progression and its potential as a therapeutic target." (PMID 40356890, 2025). "The Ca2+-activated Cl− channel ANO1 facilitates the progression of breast cancer by triggering the activation of EGFR (epidermal growth factor receptor) and CAMK (calcium/calmodulin-dependent protein kinase) signaling pathways." (PMID 40110186, 2025). "ANO1, a calcium-activated chloride channel, is a significant oncogenic factor in the 11q13 amplification of breast cancer and other malignancies." (PMID 39744692, 2025). "Recent researches have revealed that ANO1 overexpression promotes the progression of lung cancer, head and neck squamous cell carcinoma, and breast cancer through the epidermal growth factor receptor signaling pathway." (PMID 38352864, 2024). "Specifically, in breast cancer cells, ANO1, epidermal growth factor receptor, and signal transducer and transcriptional activator 3 form a positive feedback pathway that promotes cancer cell proliferation and growth." (PMID 38352864, 2024). "As an example, TMEM16A/ANO1 appears amplified and overexpressed in breast cancer, contributing to enhanced malignancy and proliferative activity via EGFR signaling pathways." (PMID 36979639, 2023). "Several recent studies have shown that ANO1 (TMEM16A) is overexpressed in many cancer types such as breast cancer, head and neck squamous cell carcinoma (HNSCC), prostate cancer, colorectal cancer, and glioma." (PMID 36497413, 2022). "In particular, the expression of ANO1 was upregulated in various human cancers including breast cancer, esophageal cancer, and head and neck cancer." (PMID 34281197, 2021). "Downregulation of MCL1 mRNA levels upon ANO1 knockdown was concordant with a decrease at the protein level, as well as with previous observations in breast cancer cell lines." (PMID 33803266, 2021). "Studies have reported that ANO1 regulates proliferation in various cells and carcinomas including interstitial cells, prostate carcinoma, breast cancer, and HNSCC." (PMID 34281197, 2021). "ANO1 knock-down in breast cancer and colorectal cancer cells induced reduction of pERK1/2 and pAKT but not of ERK1/2 or AKT expression." (PMID 34281197, 2021). "Epidermal growth factor (EGF) promotes ANO1 expression in colonic epithelial cancer cells and in breast cancer cells." (PMID 33250781, 2020). "Further, knockdown of ANO1 in breast cancer YMB-1 cells also resulted in reduced mRNA levels of HER2 EGFR, suggesting the regulation at a transcriptional level." (PMID 33250781, 2020). "In cancer research, Britschgi et al43 found ANO1 promoted breast cancer progression by CAMK and EGFR pathways." (PMID 32924329, 2020).
breast cancer (continued). "In breast cancer cells, ANO1 promotes cancer progression by stimulating the cell proliferation signaling pathway involving EGFR and CaMKII." (PMID 32357567, 2020). "The activation of EGFR signaling by ANO1 also promotes the activation of Ca2+/Calmodulin-dependent kinase II (CAMKII) signaling in breast cancer cells." (PMID 32357567, 2020). "It has been thus demonstrated that the overexpression of CLIC1 or ANO1 are correlated to the resistance of glioblastoma cancer stem cells, ovarian or breast cancer." (PMID 30884858, 2019). "Knockdown of ANO1 in breast cancer cell lines inhibited proliferation, induced apoptosis, and reduced tumor growth in xenografts." (PMID 29463274, 2018). "Knock-down of ANO1 with siRNA induced G0/G1 cell cycle arrest and significantly inhibited the invasiveness of breast carcinoma cells." (PMID 29416639, 2018). "Especially, ANO1 expression was an independent indicator of poor prognosis of shorter overall survival and relapse-free survival of breast carcinoma patients by multivariate analysis." (PMID 29416639, 2018). "In MCF7 and MDA-MB-231 breast carcinoma cells, inhibition of ANO1 with T16Ainh-A01 or siRNA for ANO1 significantly suppressed the proliferation of cells." (PMID 29416639, 2018). "Of the 407 breast cancer samples, 175 (43%) samples exhibited the low expression of Ano1, and 232 (57%) samples showed the high expression of Ano1." (PMID 29156699, 2017). "In breast cancer cell lines, Ano1 activates the epidermal growth factor receptor (EGFR) and calmodulin-dependent protein kinase (CAMK) signaling pathways." (PMID 29156699, 2017). "We performed immunohistochemistry to investigate the expression of Ano1 and Ki67 in 407 breast cancer samples." (PMID 29156699, 2017). "Our findings support the idea that Ano1 differentially regulates breast cancer cell proliferation in a cell-specific manner, depending on the ER, PR, and HER2 status." (PMID 29156699, 2017). "In the present study, we investigated the cell-specific mechanisms of Ano1 in breast cancer cell proliferation in breast cancer tumors and cell lines with different ER, PR and HER2 status." (PMID 29156699, 2017). "We then evaluated the association of the expression of Ano1 and Ki67 with the OS or DFS in breast cancer patients." (PMID 29156699, 2017). "In tumour tissue of S23 sample, i.e.23D, PLA2G16 (in arachidonic acid metabolism pathway) was found to be fused with ANO1, known to promote an aggressive phenotype in breast cancer." (PMID 28886030, 2017). "Amplification of the corresponding chromosomal region in 11q13 contributes to Ano1 overexpression in many cancers including breast cancer." (PMID 29156699, 2017). "It is unlikely that the 11q13 amplification is the only contributor to Ano1 overexpression in breast cancer." (PMID 29156699, 2017). "Evidence from breast cancer shows that ANO1 is involved in oncogenic signaling by activating EGFR and CAMK pathways to promote cancer progression." (PMID 27732935, 2016). "Although a significant correlation has been found between ANO1 expression levels and overall survival (OS) of breast cancer patients, the clinical implication of ANO1 in human malignancies remain to be elucidated." (PMID 27016410, 2016). "We studied the expression of Ano1 on 431 samples from patients with breast cancer and 46 samples from patients with fibroadenoma, using immunohistochemistry." (PMID 25961581, 2015). "We further investigated the association of Ano1 expression with the OS and DFS in subgroups of breast cancer patients, categorized according to the ER, PR, and HER2 status." (PMID 25961581, 2015). "For example, in breast cancer cell lines, Ano1 promotes breast cancer progression by activating the epidermal growth factor receptor (EGFR) and calmodulin-dependent protein kinase (CAMK) signaling pathways." (PMID 25961581, 2015). "In this study, we investigated the expression of Ano1 in 431 breast cancer patients with invasive ductal carcinoma (IDC)." (PMID 25961581, 2015).
breast cancer (continued). "Multivariate COX regression analysis of the association of Ano1 expression and clinicopathological features with RFS and OS in breast cancer patients." (PMID 25961581, 2015). "Recently, several studies have found overexpression of Ano1 in other tumors including breast cancer, prostate cancer, and chondroblastoma." (PMID 25961581, 2015). "Ano1 immunoreactivity occurred significantly more frequently in breast cancer samples than in fibroadenoma samples (p<0.001)." (PMID 25961581, 2015). "In breast cancer cells, down-regulation of the ANO1 gene expression reduced proliferation, provoked apoptosis, and inhibited tumor growth in a xenograft model." (PMID 26196390, 2015). "We evaluated the association of Ano1 expression levels with the OS and DFS in breast cancer patients, using Kaplan-Meier analysis." (PMID 25961581, 2015). "For example, several studies have shown that Ano1 overexpression promotes cell proliferation in many tumors including head and neck squamous cell carcinoma, breast cancer, and prostate cancer." (PMID 25961581, 2015). "For example, several in vitro studies have shown that Ano1 overexpression promotes cell proliferation and migration in head and neck squamous cell carcinoma, breast cancer, and prostate cancer." (PMID 25961581, 2015). "We found that ANO1 expression in breast cancer cell line, MCF7 is dramatically upregulated by some Wnt signaling factors (unpubl." (PMID 24639373, 2014). "A correlation between the expression of ANO1 and various types of cancers and diseases including urinary bladder cancer, breast cancer, head and neck squamous cell carcinoma and cystic fibrosis has been reported." (PMID 24316695, 2014). "Recently, several groups reported that anoctamin 1 (Ano1) plays a role in cancer cell proliferation; in breast cancer, it does so through the ERK/AKT signaling pathway." (PMID 24663380, 2014). "The Bentires-Alj group found that ANO1 is amplified and highly expressed in breast cancer cell lines and primary tumors." (PMID 24639373, 2014). "In contrast to ANO1, another chloride channel behaves as a candidate tumor suppressor in breast cancer." (PMID 24386311, 2013). "Breast cancer cells overexpressing it had a proliferative advantage, while knockdown or pharmacological inhibition of ANO1 in those cell lines reduced colony size in vitro." (PMID 24386311, 2013). "The ANO1 (TMEM16A) channel is inhibited by CaCCinh-A01, which impedes breast cancer progression." (PMID 41155636, 2025). "Anoctamin1 (ANO1) is a calcium-activated chloride channel (CaCC) that is widely expressed in a variety of human carcinomas, including head and neck squamous cell carcinoma, esophageal squamous cell carcinoma, oral cancer, breast cancer, and prostate cancer." (PMID 38773164, 2024). "With regard to the underlying molecular mechanism of tumorigenesis induced by ANO1, previous studies identified ANO1 to promote development of breast cancer, growth of colorectal cancer, and cell proliferation in benign prostatic hyperplasia (BPH) through an increase in phosphorylated ERK1/2 or AKT." (PMID 34281197, 2021). "Calcium-activated chloride channel ANO1 was found to promote breast cancer progression." (PMID 31557971, 2019). "In contrast to ANO1, the cystic fibrosis transmembrane conductance regulator (CFTR), mutations of which are responsible for cystic fibrosis, is another chloride channel that acts as a candidate tumor suppressor in breast cancer." (PMID 29463274, 2018). "In conclusion, this study demonstrates that ANO1 expression is an indicator of poor prognosis of breast carcinoma patients and suggests that ANO1 might be a therapeutic target for breast carcinoma patients with ANO1-positive tumors and poor prognosis." (PMID 29416639, 2018). "Therefore, we investigated the expression of ANO1 in 139 breast carcinoma patients and the role of ANO1 in vitro." (PMID 29416639, 2018).
breast cancer (continued). "The poor prognosis of breast cancer patients with the high expression of Ano1 may be explained by the proliferation-promoting effect of Ano1 as identified in MCF7 cells." (PMID 29156699, 2017). "However, in human breast cancer samples, we found that Ano1 expression was negatively correlated with Ki67 expression." (PMID 29156699, 2017). "It appears that Ano1 overexpression may inhibit cell proliferation in human breast cancer with ER-positive or HER2-negative status." (PMID 29156699, 2017). "Meanwhile, Ca2+-activated Cl− channel transmembrane protein 16A (TMEM16A, also known as ANO1) could promote breast cancer progression by activating calmodulin-dependent protein kinase (CAMK) and epidermal growth factor receptor (EGFR) signaling." (PMID 28264681, 2017). "It has been reported that the inhibition of histone deacetylase (HDAC) downregulated Ano1 expression in breast cancer cells, suggesting that epigenetic regulation of Ano1 by HDAC may contribute to Ano1 overexpression in breast cancer." (PMID 29156699, 2017). "Combined expression of Ano1 and Ki67 may be used for predicting clinical outcomes of breast cancer patients with different subtypes of ER, PR, and HER2." (PMID 29156699, 2017). "The proliferation-promoting effect of Ano1 in MCF7 cells may represent a specific feature of a certain breast cancer cell population and/or under a certain cellular condition." (PMID 29156699, 2017). "Ano1 overexpression was associated with longer overall survival (OS) in breast cancer with the low expression of Ki67, especially in ER-positive, PR-positive, and HER2-negative breast cancer." (PMID 29156699, 2017). "Our findings suggest that Ano1 may differentially regulate cell proliferation in a subtype of breast cancer defined by ER, PR, and HER2." (PMID 29156699, 2017). "The role of Ano1 in breast cancer tumorigenesis may be explained by a cell-type specific mechanism defined by different ER, PR and HER2 status." (PMID 29156699, 2017). "We and others have previously reported that Ano1 is overexpressed in breast cancer." (PMID 29156699, 2017). "In addition, histone deacetylase (HDAC) inhibitors downregulated ANO1 expression and its activity in prostate or breast cancer cell lines, resulting in suppression of cancer cell viability." (PMID 26811235, 2016). "Although Ano1 is overexpressed in breast cancer, it remains unclear whether Ano1 overexpression promotes tumor development in breast cancer patients." (PMID 25961581, 2015). "Our study suggests that Ano1 may be a potential marker for good prognosis in breast cancer patients with the PR-positive, or HER2-negative status." (PMID 25961581, 2015). "Ano1 is overexpressed in many tumors, including breast cancer." (PMID 25961581, 2015). "Therefore, Ano1 expression levels have both prognostic and predictive values for breast cancer patients." (PMID 25961581, 2015). "Ano1 overexpression was found in many cancers with 11q13 amplification, including breast cancer." (PMID 25961581, 2015). "Although Ano1 overexpression is found in breast cancer due to 11q13 amplification, it remains unclear whether signaling pathways are involved in Ano1 overexpression during breast cancer tumorigenesis in vivo." (PMID 25961581, 2015). "Interestingly, tamoxifen has been found to inhibit chloride channels, including Ano1, and inhibition of Ano1 currents reduces breast cancer cell survival." (PMID 25961581, 2015). "The findings that Ano1 is overexpressed in breast cancer compared with benign fibroadenoma and tumor-adjacent normal breast tissues suggest that Ano1 overexpression may contribute to malignant transformation of mammary epithelial cells into breast cancer." (PMID 25961581, 2015). "It is unknown whether signaling pathways or transcription factors are involved in Ano1 overexpression in breast cancer tumorigenesis in vivo." (PMID 25961581, 2015). "Clinicopathological characteristics in breast cancer patients with Ano1 expression." (PMID 25961581, 2015).
breast cancer (continued). "To date, it remains unclear whether Ano1 is associated with the ER, PR, and HER2 status and clinical outcomes in breast cancer patients receiving endocrine treatment." (PMID 25961581, 2015). "Ano1 immunoreactivity was observed in 395 (91.6%) of 431 breast cancer samples." (PMID 25961581, 2015). "Our finding that Ano1 overexpression was associated with good prognosis in PR-positive or HER2-negative breast cancer patients following tamoxifen treatment suggests that Ano1 overexpression is a predictive factor for tamoxifen benefit in these subgroups of breast cancer patients." (PMID 25961581, 2015). "Correlation of Ano1 expression with clinicopathological parameters in patients with breast cancer." (PMID 25961581, 2015). "Furthermore, we examined Ano1 expression in breast cancer patients with different ER, PR, and HER2 status." (PMID 25961581, 2015). "It is possible that inhibition of Ano1 channels by tamoxifen may contribute to the beneficial effect of tamoxifen treatment in PR-positive breast cancer patients." (PMID 25961581, 2015). "Ano1 overexpression has been found to be due to amplification of the corresponding chromosomal region in 11q13, and correlates with poor prognosis in patients with breast cancer and head and neck squamous cell carcinoma." (PMID 25961581, 2015). "Ano1 was overexpressed in breast cancer compared with fibroadenoma." (PMID 25961581, 2015). "In HER2-negative breast cancer, EGFR signaling activation by Ano1 may contribute to breast cancer tumorigenesis, and thus Ano1 inhibition by tamoxifen may result in good prognosis in HER2-negative patients receiving tamoxifen treatment." (PMID 25961581, 2015). "Since high-expression level of ANO1 occurs in the breast cancer, we tested several Wnt pathways to see which one may be correlated with the ANO1 overexpression." (PMID 24639373, 2014). "Amplification of ANO1 in breast cancer was correlated with disease grade and poor prognosis." (PMID 24639373, 2014). "ANO1 channel function was also important for breast cancer cell viability." (PMID 24639373, 2014). "Moreover, ANO1 has garnered significant attention for its role in the development and progression of cancers, including head and neck cancer, breast cancer, and lung cancer, where its overexpression correlates with increased tumor growth, metastasis, and poor prognosis." (PMID 40356890, 2025). "One study showed that inhibition of CaMK2 signaling partially abolished ANO1’s promotion of cell viability and proliferation in ANO1-replicated and overexpressed breast cancer and concluded that CaMK2 may play a critical role in cellular proliferation and oncogenesis in breast cancer." (PMID 40579643, 2025). "However, the role of ANO1 in breast carcinoma has been controversial." (PMID 29416639, 2018). "Therefore, in the future, Ano1 expression could be used to help better identify Luminal A breast cancer patients with more sensitivity to tamoxifen treatment." (PMID 29156699, 2017). "In addition, although the 11q13 amplification contributes to Ano1 overexpression in human breast cancer, it is unlikely the major contributor to Ano1 overexpression in PR-positive tumors, because the 11q13 amplification only occurs in approximately 15% of human breast cancer." (PMID 25961581, 2015). "In addition, we found that Ano1 overexpression was associated with longer OS in HER2-negative, but not HER2-postive, patients following tamoxifen treatment, suggesting that HER2 signaling may be involved in the role of Ano1 in breast cancer development." (PMID 25961581, 2015). "Since Ano1 overexpression did not correlate with clinical stage and histological grade in ER-negative, PR-positive, PR-negative, and HER2-postive tumors, cell-type specific mechanisms may be responsible for different roles of Ano1 in breast cancer cells with different ER, PR, and HER2 status." (PMID 25961581, 2015). "Combined blockade of ANO1 and EGFR remarkably improved response to cetuximab in HNSCC and breast cancer." (PMID 40396170, 2025).